IL6 (interleukin 6)
Diseases named in the same sentence as IL6 in open-access papers (continued):
Sharing a sentence is not in itself a finding about the gene and the disease.
tumor (continued). "Free radical scavenging activities of CUR, as well as a decrease in the expression of inflammatory cytokines IL-1b, IL-6, and TNF- α, result in decreased cancer growth and down-regulation of enzymes such as protein kinase C, which regulate inflammation and tumor cell proliferation." (PMID 35159669, 2022). "Although exercise training improves phenotypic characteristics in male ApcMin/+ mice, such as lean mass and motor function, 5-week voluntary wheel running does not decrease either tumour burden or the elevated circulating IL-6 levels." (PMID 35626116, 2022). "In addition, HMGB1 promotes the release of IL-6 and IL-8 by activating MAPK- and MyD88-dependent NF-κB pathways, resulting in promoted tumor proliferation, angiogenesis, EMT, invasion and metastasis." (PMID 35493517, 2022). "In addition to EGFR, IL-6 signaling also activates STAT3, and IL6R blockade significantly inhibits tumor progression." (PMID 36010693, 2022). "Previous studies have shown that tumor cell-induced neutrophil ETs could stimulate immune cells to release inflammatory cytokines, including IL-1, IL-6, ICAM-1, VCAM-1, and E-selectin, leading to tumor growth." (PMID 36325339, 2022). "Interestingly, in the TME A2AR activation has been reported to reduce the production of those tumor eradicating cytokines IL-6, IL-17, and IFN-γ that in the present study we found downmodulated in tumor-bearing p2x7−/− mice." (PMID 35663396, 2022). "Although cytokine expressions of TNF-α, IL-6, IL-17A, and TGF-β1 are sensitive phenotyping biomarkers in radiation-induced cardiopulmonary toxicities, they are not specific in differentiation of inflammation/infection versus tumor recurrence." (PMID 36591530, 2022). "High TNF and interleukin-6 (IL-6) levels, which are known to be responsible for the proliferation and metastatic potential of tumor cells, indicate a negative prognosis for the patient." (PMID 35740575, 2022). "The miR-21a in exosomes from Lewis lung carcinoma cells accelerates tumor growth through targeting programmed cell death protein 4 (PDCD4) through activating the autocrine production of IL-6 and phosphorylation of the STAT3 signaling pathway and thus enhances the expansion of MDSCs and tumor growth." (PMID 35634311, 2022). "In the TME, senescent tumor cells may increase antitumor immune responses by secreting IL-6, IL-8, and insulin-like growth factor binding protein 7 (IGFBP7) with the ability of recruiting immune cells such as T lymphocytes to the tumor site." (PMID 36518628, 2022). "Furthermore, BMSCs release IL-6 and IGF-1, which activate the signal transduction pathways that mediate drug resistance and increase the activation of HIF-1, affecting tumor metabolism and drug resistance." (PMID 36362718, 2022). "Indeed, IL-17 induces IL-6 production that in turn activates STAT3-dependant pathways, thereby promoting the proliferation of HepG2 cells in vitro and tumor growth after orthotopic liver transplantation." (PMID 35342340, 2022). "For example, GM-CSF and IL6 induced BM cells to differentiate in highly suppressive MDSCs28 that promoted tumor cell proliferation and did not induce clonotypic T cell proliferation when pulsed with the relevant peptide." (PMID 35064009, 2022). "Clearly therefore, it might be too simple an expectation to solely rely on an exercise-induced reduction to IL-6 (and CRP) to promote a T cell reactive environment in the tumour." (PMID 35359426, 2022). "Secondly, indicators such as Helicobacter pylori infection, carbohydrate antigen 724, peripheral blood circulating tumor cells and interleukin-6 were not included in the study, and the accuracy of the model needs to be further improved." (PMID 36684356, 2022). "Additionally, cytokines and growth factors in the TME, particularly IL-6, EGF, and hepatocyte growth factor, suppress anoikis by activating tumor cell signaling pathways, including the RAS-MAPK, PI3K-mechanistic target of rapamycin kinase, and STAT3 pathways." (PMID 36010693, 2022).
tumor (continued). "IL6/JAK/STAT3 signalling was enhanced in M1-like MΦ of the CCI patient group, which was also activated in the mouse model in the resident-like MΦs, in TC1 tumours treated with the caerin peptide gel." (PMID 36497272, 2022). "Autophagosomes-induced CD4+ T cells in an IL-6- and IL-10-dependent manner suppress CD4+ and CD8+ effector T cell functions and induce IL-10-producing Breg cells via IL-6, IL-10 and IL-21, thereby promoting tumor growth and metastasis." (PMID 36365103, 2022). "The role of CHD1L has been thoroughly described in cancer literature to drive tumour proliferation lead to poor cancer prognosis possibly by regulating immune factors in regulating apoptosis such as CD8+ T-cell populations and IL-6 levels." (PMID 35354798, 2022). "In stage I and II of COAD, IL6/STAT3 signaling pathway, TGF-β signaling and FC receptor response have strong activity, which revealed the inflammatory activation of the immune response in the early stage of the tumor." (PMID 35992347, 2022). "Inflammatory cytokines such as IL-6, IL-21, IL-1β, and TNF-α diminish the cytotoxic capacity of immune CD8+ T cells to produce IFN-γ, which plays a main role in angiogenesis and MHC expression—tumor recognition." (PMID 35681689, 2022). "TAFs are able to stimulate tumor cell proliferation through the secretion of various growth factors, hormones, and cytokines, including hepatocyte growth factor (HGF), FGFs, SDF-1, and IL-6." (PMID 35741334, 2022). "Neutralization of BL1 autocrine IL-6 provided no benefit in reducing tumor cell proliferation in vivo." (PMID 35260569, 2022). "Then, IL-6, in turn, increases the level of MMP2, MMP9, and MMP13 to promote tumor cell invasion." (PMID 35741075, 2022). "Additionally, we acquired a total of 6 molecules including IL6, AREG, CXCL12, TGFβ, VEGF and CCL2, which can be upregulated upon senescence, influence immune cell functions, and play tumor-promoting roles in TME30." (PMID 35361903, 2022). "The expansion of fibroblasts is seen in the early tumour stage where CAFs act as “tumour suppressors”, producing gap junctions which subsequently turn CAFs into “tumour promoters”, as activated by tumour-secreted factors such as PDGF, FAP, interleukin-4, interleukin-6 and prostaglandin E (PGE)." (PMID 36101394, 2022). "Multiple cytokines in tumor microenhractures such as TNF-α, IFN-γ, IL-6, and IL-10 play a synergistic role by increasing the expression of IDO1, affecting catabolism of tryptophan, and promoting immunosuppressive response, which in turn promotes the initiation of cancer." (PMID 35444235, 2022). "Additionally, IL-6, a chronic inflammatory protein that induces CRP expression, was also reported to have a potential immune suppressive function and promote tumor progression by inducing tumor cell expression of STAT3 and its downstream target genes." (PMID 35185894, 2022). "Importantly, the magnitude of tumor hypoxia (i.e., HSV) remained the only significant parameter for IL-6 plasma concentrations in the multiple regression analysis." (PMID 34773163, 2022). "Additionally, shAPE1‐loaded RCSC‐EVs suppressed the Erlotinib resistance of NSCLC via the IL‐6/STAT3 axis both in vitro and in vivo, as reflected by impeded malignant phenotypes and xenograft tumour formation." (PMID 35605028, 2022). "Tumor cells can change the immune status of the tumor microenvironment by upregulating programmed death-ligand 1 (PD-1), and related inflammatory factors such as TNF-a, IL-6, and IL-1β increase significantly." (PMID 36189281, 2022). "Furthermore, C3a and C5a are efficient stimulators of inflammatory mediators like IL-1β, IL-6 and TNF-α, and inflammatory processes are vital for tumor development, promoting subthreshold neoplastic tumor states to fully cancerous states." (PMID 36547187, 2022).
tumor (continued). "These include chronic inflammation triggering cell transformation, stimulation of pro-inflammatory cytokines (IL-6, IL-8, and TNF), alteration of the tumor microenvironment, and production of reactive oxygen species (ROS) and nitric oxygen synthase (NOS) that can lead to DNA damage." (PMID 35678665, 2022). "Consistent with elevated IL-6, oxidative stress, STAT3 phosphorylation, and muscle wasting, we demonstrated elevated expression of key genes and protein levels of UPS and autophagy pathways in tumor-bearing mice compared to controls." (PMID 35847939, 2022). "Previous studies showed that PD-1 blockade led to the augmentation of effector T cells in tumor sites, increasing the cytolytic activity of tumor-specific cells, increasing production of IL-2, INF-γ, TNF-α, IL-17, and IL-6, and decreasing the production of the Th2 cytokines such as IL-5 and IL-13." (PMID 35996120, 2022). "STAT3 silencing also could reduce the expressions of cytokines IL-6, IL-1β and inflammatory mediators ICAM1 and COX2 in the tumor microenvironment." (PMID 35513871, 2022). "Numerous studies have indicated leptin, IL-6, and TNF-α could enhance the metastatic properties of tumor cells by activating of NF-KB or STAT3 signal pathway." (PMID 36361525, 2022). "IL-6/STAT3 signaling is required for the maintenance of breast CSCs and tumor growth." (PMID 36010693, 2022). "Factors released by adipocytes, represented by leptin, insulin, and IL-6, can domesticate macrophages toward the function of promoting tumor malignancy, manifested by the changes in the secretion profile of macrophages, including pro-angiogenic VEGF and pro-inflammatory IL-6." (PMID 35701840, 2022). "Inflammatory cytokines, such as IL-6, tumor necrosis factor and vascular endothelial growth factor VEGF produced by neutrophils activation may enhance tumor growth." (PMID 35797279, 2022). "Pre-incubation of tumor cells with LPS induced lower IL-6 release by irradiated cells as compared with non-irradiated cells." (PMID 35335367, 2022). "Therefore, IL-6 may re-educate the lung microenvironment towards an anti-inflammatory phenotype, limiting inflammation via polarization of anti-inflammatory macrophages, recruitment of MDSCs and Treg/Th17 increasing response, favoring tumor immune escape and growth." (PMID 35159208, 2022). "Inhibited the expression of PPP2CA, which could promote the release of pro-inflammatory cytokines such as IL-1b, IL-6, and TNF-a from macrophages stimulating tumor invasion." (PMID 36612080, 2022). "Xenotransplantation models have shown that M2 macrophages-derived exosomes carrying miR-155-5p can upregulate IL-6 and affect its stability by disrupting ZC3H12B-mediated mechanisms, that may induce immune escape and tumor formation in colon cancer." (PMID 36741380, 2022). "In our cell experiments, TNF-α and IL-6 were highly expressed in PRAD cell lines and positively regulated by ARRB2, suggesting that ARRB2 could affect PRAD tumor progression by regulating the expression of IFs." (PMID 36284990, 2022). "In colon cancer, CAF-derived IL-6 induces VEGFA production in an autocrine or paracrine manner, and CAF-derived IL-8 is induced by the autocrine Chitinase 3-like 1, which both promote tumor angiogenesis." (PMID 35327514, 2022). "Intra-tumor increased IL-2, IFN-γ, and GM-CSF and decreased IL-6 staining." (PMID 36358823, 2022).
tumor (continued). "Furthermore, M1 macrophages express proinflammatory cytokines like TNFα, IL-6, and CXCL10, present antigen to immune cells and phagocytize tumor cells." (PMID 35419058, 2022). "In the tumor microenvironment, increased C–C motif chemokine ligand 2 [CCL2, also known as monocyte chemoattractant protein-1 (MCP-1)] and IL-6 induce the recruitment of myeloid-derived suppressor cells (MDSCs), which are known to be immune-suppressive cells that inhibit antitumor immunity." (PMID 36380016, 2022). "Furthermore, ADAM17 is able to promote tumor growth via induction of inflammatory processes, such as TNF α signaling and interleukin 6 (IL-6) trans-signaling." (PMID 36078095, 2022). "IL-6 can be secreted in an autocrine or paracrine manner by both immune and non-immune cells in the tumor microenvironment." (PMID 35371975, 2022). "In addition, neutrophils contribute to tumor angiogenesis by delivering angiogenic factors including VEGF, protease, IL-1, IL-6 and IL-8, and eventually resulting in tumor progression." (PMID 35662746, 2022). "Simvastatin could decrease CCL3 expression from cancer cells and ICAM-1, VCAM1, IL-6, and CCL2 expression from CaMSCs, disrupting the crosstalk of the cancer cells and tumor microenvironments (TME) and inhibiting tumor progression." (PMID 36430409, 2022). "In a xenograft model of adenocarcinoma, the anti-IL-6 antibody siltuximab exhibited more potent effects in tumor cells in the presence of CAFs than without these cells." (PMID 36422541, 2022). "MiR142-3p mimics could block IL-6, HMGA2, and SOX2 expression in GBM tumor cells that inhibit tumorigenicity." (PMID 35572545, 2022). "Neutrophils can also release matrix metalloproteinase-9 (MMP9), vascular endothelial growth factor (VEGF), and inflammatory mediators, such as interleukin 6(IL-6) and tumor necrosis factor-β (TNF-β), which promote the invasion, proliferation and distant metastasis of tumor cells." (PMID 35570842, 2022). "Additionally, CSCs secrete immunosuppressive cytokines and other molecules that convert immune cells into tumor allies, such as transforming growth factor (TGF)-β, interleukin (IL)-6, IL-8 and vascular endothelial growth factor (VEGF)." (PMID 35530300, 2022). "At the same time, it can also promote the formation and maintenance of tumor stem cells by increasing the expressions of IL-10 and TGF-β (transforming growth factor-β) in TIME, and reduce the expressions of IL-1, IL-6, IL-12 and TNF-α (transforming growth factor-α)." (PMID 35402261, 2022). "A related strategy is to alter the tumor milieu through druggable targets such as CXCR4, IL-6, IGF-1, VEGF, their cognate receptors, and RANKL in combination therapy to target the cytokines involved in cell adhesion has shown promise whereas monotherapy has been ineffective." (PMID 36212502, 2022). "Given the redundancy in IL6/LIF signaling through the GP130 coreceptor and downstream JAK/STAT signaling cascade, tumors were scored as positive if they expressed either cytokine in the tumor microenvironment." (PMID 36230597, 2022). "Likewise, CAFs are involved in monocyte recruitment, macrophage differentiation, and polarization toward tumor-promoting, or an M2 phenotype, through the secretion of macrophage colony-stimulating factor 1 (M-CSF1), IL-6, CCL2, and IL-8." (PMID 36010899, 2022). "Our group has previously demonstrated that miR-26a could suppress the tumor growth and metastasis of HCC through IL-6/STAT3 signaling." (PMID 35432524, 2022). "Fra-1 can increase the production of the cytokine IL-6 and skew RAW264.7 macrophage cell differentiation into M2d macrophage, then promotes tumor metastasis and progression; CD137 promotes the migration of monocytes/macrophages to tumor microenvironment by upregulating the expression of Fra1." (PMID 36032067, 2022).
tumor (continued). "The activation of REG3A will enhance the JAK2/STAT3 pathway and form a positive feedback loop of REG3A-JAK2/STAT3, thereby amplifying the carcinogenic effect of IL-6/JAK2/STAT3, and ultimately leads to excessive PC cell proliferation in vitro and in vivo and tumor formation." (PMID 36591515, 2022). "Nevertheless, is well-known that MCs through releasing IL-1, IL-4, IL-6, IL-8, TNF-α, IFN-γ, TGF-β, MCP-3, MCP-4, leukotriene B4 (LTB4) and chymase can contribute to inflammation, inhibition of tumour cell growth, and induction of tumour cell apoptosis." (PMID 35406451, 2022). "Tumor cells activate platelets through direct cancer cell–platelet adhesion, and/or by tumor secretion of platelet-activating molecules (i.e., ADP, thrombin, matrix metalloproteinases, IL-6) which lead to platelet adhesion/aggregation." (PMID 35204760, 2022). "In control-treated tumour specimens, there were strong negative correlations between IL-6 secretion and age, IL-6 secretion and chromosome 8 alterations, and VEGF-A secretion and largest ultrasound height." (PMID 36698840, 2022). "Disruption of the IL-6/IL-6R/STAT-3 axis using Stt and Tcz may be a therapeutic target in PCa based on the molecular characteristics of the tumor cells." (PMID 35703345, 2022). "Consistently, loss of SHP-2 in BMDMs induces decreases in M1 macrophage-related gene expression (iNOS, IL-6, and TNF-α) and increases in M2 macrophage-related gene expression [Arg1, Fizz1, Ym-1, and IL-10] to promote M2 polarization of TAMs in the tumor microenvironment." (PMID 36380016, 2022). "When EVsMMA-MRC5 were collected from fibroblasts that were co-treated with antioxidants, they were no longer able to activate IL-6/JAK/STAT3 or TGFβ signaling in A549 tumor cells." (PMID 36266345, 2022). "IL-6 levels in week 2 were higher in patients with absent early tumor hypoxia response (p=0.016) and predicted early hypoxia response (AUC=0.822, p=0.031)." (PMID 34773163, 2022). "Furthermore, many growth factors and proinflammatory cytokines, including interleukin 6 (IL-6), TGF-β, and vascular endothelial growth factor (VEGF) can be produced by CAFs, which can promote tumor growth, angiogenesis, and assists in immune escape." (PMID 36010993, 2022). "Activation of STAT3 by IL-6 allows expression of cell cycle-promoting proteins such as cyclin D1, D2, and c-MYC and downregulation of cyclin-dependent kinase inhibitor p21, facilitating entry into the cell cycle, thus enhancing the growth of the tumour." (PMID 36429126, 2022). "Prostaglandins and other lipid mediators of inflammation are produced quickly by the macrophages and then their actions are followed by those of cytokines such as IL-6 and interleukin-10 (IL-10) with the consequent activation of the EGFR signal, promoting the proliferation of tumor cells." (PMID 36432658, 2022). "MSCs could sense cancer as a damaged tissue thereby migrating towards it in response to tumor-derived inflammatory molecules, such as SDF-1, TNF-a and interleukins IL-6 and LL-37." (PMID 35111750, 2021). "TGF-β, IL-6, and TNF-α play a role in tumor formation in conditions of chronic inflammation." (PMID 33567693, 2021). "As for anti-tumor responses, whereas cytokine responses were mostly absent in nerve-intact mice, IL-17A, IL-6, and IL-10A were found elevated in sympathectomized tumor-bearing mice." (PMID 33691777, 2021). "Additionally, UVB light treatment was found to reduce IL-6 levels and attenuate MDSC recruitment in tumor-bearing mice following RT." (PMID 34109109, 2021). "Indeed, we show that combined inhibition of BRD4 and IL6/8-JAK2 signaling is required to inhibit oncogene expression more completely, reversed the BETi resistance in vitro, and suppress the CRC xenograft tumor growth empowered by CAF in vivo." (PMID 34290255, 2021).